HOXA10-HOXA9 (HOXA10-HOXA9 readthrough)
Synonyms: HDSP
Gene: Protein-coding gene on chromosome 7 (27,162,438 to 27,180,239, reverse strand). Ensembl gene ENSG00000257184.
Genetic constraint (gnomAD): Loss-of-function variants: 11 observed, 13.27 expected, observed/expected ratio (o/e) 0.83, 90% interval 0.52 to 1.37. Missense variants: 158 observed, 150.38 expected, observed/expected ratio (o/e) 1.05, 90% interval 0.92 to 1.2. Synonymous variants: 57 observed, 54.56 expected, observed/expected ratio (o/e) 1.04, 90% interval 0.84 to 1.3.